IL10 (interleukin 10)
Diseases named in the same sentence as IL10 in open-access papers (continued):
Sharing a sentence is not in itself a finding about the gene and the disease.
bacterial pneumonia (21 papers, 2012 to 2025). Acute infection of the lung parenchyma caused by bacteria (e.g., Streptococcus pneumoniae, Haemophilus influenzae, Chlamydia pneumoniae, Mycoplasma pneumoniae, and Legionella pneumophila). "Similar findings showed that higher IL-10 levels at admission were associated with more severe bacterial pneumonia with prolonged hospitalization and higher mortality risk." (PMID 41018059, 2025). "Although prior studies have shown mixed results, there is evidence in a post-influenza pneumococcal pneumonia model that IL-10 contributes to enhanced susceptibility to secondary bacterial pneumonia." (PMID 25651926, 2015). "The anti-inflammatory IL-10 is an important regulator of the immune response to bacterial pneumonia which suppresses the ability of neutrophils to kill S. pneumoniae and regulates lung inflammation." (PMID 39858309, 2025). "The anti-inflammatory cytokine IL-10 is an important regulator of the immune response to bacterial pneumonia." (PMID 37381945, 2024). "The role of these cells in the resolution of bacterial pneumonia through an IL-10-dependent mechanism was demonstrated in a previous study." (PMID 28306733, 2017). "Immunosuppression mediated through IL-10 can increase mortality because it hampers the effective clearance of infectious agents in an experimental setting of bacterial pneumonia while inhibition of IL-10 bioactivity prolongs survival in a similar setting." (PMID 24804272, 2014). "A high level of IL-10 can result in increased bacterial outgrowth and markedly increased lethality during secondary bacterial pneumonia." (PMID 23369570, 2013). "The IL-10 anti-inflammatory cytokine has an important role in the evolution of bacterial pneumonia." (PMID 40654579, 2025). "This may suggest that IL-10 is a distinctive biomarker between critical COVID-19 pneumonia and bacterial pneumonia." (PMID 40508859, 2025). "Accordingly, almost all of the patients with an AAT/IL-10 ratio of ≥ 65 had bacterial pneumonia." (PMID 37876022, 2023). "Logistic regression analysis using dichotomized variables at the cutoff values showed that the odds ratios for the diagnosis of bacterial pneumonia were 10.4 for sputum volume score and 19.8 for AAT/IL-10 ratio." (PMID 37876022, 2023). "IL-8, IL-10, IL-12, TNF-α, and IFN-γ were significantly increased in bacterial pneumonia and SARS-Cov-2 compared to healthy controls." (PMID 38585537, 2023). "Cohen and Prince showed that during bacterial pneumonia type III IFNλ promotes inflammation by inhibiting miR-21, upregulating PDCD4, and consequently diminishing IL-10 production." (PMID 29942317, 2018). "Because cytokines are important regulators of the inflammatory response to bacterial pneumonia, we measured pulmonary (TNF-α, IL-6, IL-10, CXCL1) and systemic (TNF-α, MCP-1, IL-6, IFN-γ, IL-10, IL12p70) cytokine and chemokine levels." (PMID 26215706, 2014). "Our results suggest IL-10 does not respond to bacterial infection and remains below abnormal levels (5 pg/mL) in the early stage of bacterial pneumonia." (PMID 37876022, 2023). "Therefore, a decision tree using sputum volume, IL-10, and AAT can be useful in predicting bacterial pneumonia and promoting the appropriate use of antibiotics, even when airway specimens are not easily collected, as in the case of the COVID-19 pandemic." (PMID 37876022, 2023). "Since IL-10 and AAT change in contrasting directions, we propose that an AAT/IL-10 ratio of 65 or more is a good predictor of bacterial pneumonia, regardless of disease severity at diagnosis." (PMID 37876022, 2023). "With our ultimate goal being to understand the mechanism of compromised IL-10 expression under conditions of non-resolving bacterial pneumonia, we verified involvement of this mechanism in mice infected with K. pneumoniae." (PMID 28074841, 2017).
bacterial pneumonia (continued). "Gram-negative bacteremia, bacterial pneumonia, Kawasaki disease, and active SJIA exhibited similar cytokine profiles with elevated interleukin-6 (IL-6) and/or IL-10, further suggesting a correlation between them." (PMID 37828529, 2023).
Burkitt lymphoma (21 papers, 2008 to 2024). A rare form of malignant mature B-cell non-Hodgkin lymphoma. "Alterations in IL-10 have also been implicated in children with EBV-associated endemic Burkitt lymphoma." (PMID 38179040, 2023). "LMP1, a functional CD40 ortholog encoded by EBV, is both IL-10 responsive and induces secretion of cellular IL-10 in stimulated Burkitt's lymphoma cells." (PMID 18389062, 2008). "Hypoxia-induced ADSCs produced interleukin 10 (IL-10), which promoted the growth of Burkitt’s lymphoma cells." (PMID 39063048, 2024). "The authors concluded that the combination of immune regulation from IL-10 and decreased IFN-γ CD4+ T cells in EBV-associated endemic Burkitt lymphoma reduced T cell function." (PMID 38179040, 2023). "Burkitt lymphoma cells, an EBV-associated tumor, induce IL-10 by EBER, and proliferate using IL-10 as an autocrine self-growth factor." (PMID 34638279, 2021). "Burkitt’s lymphoma children and adolescents in the study setting showed moderately higher levels of IL-6, IL-17A, IL-10 but low levels of IL-2, TNF-α and IFN-γ, possibly determined by prevailing infections." (PMID 29078819, 2017). "It was reported that rituximab is able to inhibit STAT3 activity and IL-10 secretion by a CD20 positive Burkitt's lymphoma cell line, 2F7." (PMID 26315113, 2015). "Previously, LMP1 has been shown to induce IL-6 and IL-8 secretion in epithelial cells via the NF-κB pathway and IL-10 in Burkitt lymphoma cells." (PMID 24886620, 2014). "Approximately 10 fold increased expression of the IL-10 in Burkitt's lymphoma cell lines is reported." (PMID 21791113, 2011). "Among immunomodulatory cytokines, IL-10 was a particularly interesting candidate in our context, because it is constitutively produced at high levels by EBV-transformed B cells, and a recent report showed that LMP2A increased IL-10 production in Burkitt lymphoma cell lines." (PMID 26067064, 2015). "A significant M infiltration is observed in other aggressive B-cell lymphomas such as in Burkitt's lymphoma (BL), in which Ms are functionally involved in neoplastic apoptotic cell engulfment and are stimulated by IL-10 to the synthesis and release of B-cell trophic factors such as BAFF/BLyS." (PMID 22400028, 2012). "EBER-induced interleukin (IL)-10 expression in Burkitt's lymphoma (BL) cells has been demonstrated." (PMID 18957101, 2008). "Furthermore, EBERs induce interleukin-10, an autocrine growth factor for Burkitt’s lymphoma cells, by activating RIG-I/interferon regulatory factor 3 pathway, suggesting that EBER-mediated innate immune signaling modulation contributes to EBV-mediated oncogenesis." (PMID 25101570, 2014). "We conducted the functional analysis of the regulatory elements of human IL10 locus using a double luciferase assay in immortalized pro-B cell line Reh (B cell acute lymphoblastic leukemia, B-ALL), and Namalwa and Raji B cells from Burkitt’s lymphoma, which represent germinal center B cells." (PMID 39337678, 2024). "Furthermore, cocultures of NLRP11-expressing Burkitt's lymphoma cells and naïve human peripheral CD4+ T lymphocytes had reduced IFN-γ and IL-17A production, whereas IL-13 and IL-10 cytokines did not change." (PMID 32832566, 2020).
chronic lymphocytic leukemia (21 papers, 2010 to 2025). "Chronic lymphocytic leukemia also secretes IL-10 and TGF-β and relies on stromal interactions to support tumor survival; these features are associated with disease progression and therapy resistance." (PMID 40801653, 2025). "The CXCL12/CXCR4/STAT3 pathway can promote the expression of IL-10 in chronic lymphocytic leukemia (CLL) cells, inducing immunosuppression." (PMID 38920657, 2024). "IL-10 signaling blockade significantly impaired the maintenance of Tpex in the mouse model of chronic lymphocytic leukemia (CLL) and accelerated the development of exhaustion." (PMID 37398660, 2023). "In particular, human and mice monoclonal chronic lymphocytic leukaemia B cells increased intracellular IL-10 production upon stimulation with BAFF and CpG versus either condition alone, and this was reduced by blocking TACI." (PMID 34122439, 2021). "Chronic lymphocytic leukemia (CLL) cells produce IL-10 via STAT3 signaling, which can suppress T cell effector function." (PMID 30420856, 2018). "Ibrutinib, a Bruton's tyrosine kinase inhibitor, was shown to down-regulate PD-L1 expression on tumor cells and PD1 in CD4+ and CD8+ T cells via inhibition of STAT3 and also decreased IL-10 production by chronic lymphocytic leukemia (CLL) cells in patients." (PMID 30420856, 2018). "Elevated CD1d expression is detected in CD5+ IL10-producing B cells, called B10 B cells, and is correlated with poorer prognosis in chronic lymphocytic leukemia (CLL), a CD5+ B cell malignancy with B10-like functional properties." (PMID 26537916, 2015). "In a malignant B-1 cell line derived from a murine model of chronic lymphocytic leukaemia, induction of RNAi against IL-10 resulted in anti-proliferative and pro-apoptotic effects." (PMID 20836854, 2010). "Despite its involvement in various biological processes, the role of IL-10 in the development and progression of B-cell chronic lymphocytic leukemia (CLL) remains unclear." (PMID 37048814, 2023). "In chronic lymphocytic leukemia (CLL), STAT3 is required to PD-L1 expression and IL-10 production which in turn seems to be responsible for PD-1 expression in CD4+ and CD8+ T-cells." (PMID 31480382, 2019). "IL-4 and IL-10 are also secreted by AML and chronic lymphocytic leukemia (CLL) cells, and these cytokines support the CLL immune escape program." (PMID 31485227, 2019). "IL-10 is overexpressed in human chronic lymphocytic leukemia (CLL) and human malignant CLL cells can produce autocrine IL-10." (PMID 28072868, 2017). "Previous study reported that IL-10 could promote tumorigenesis or progression through STAT3 signaling in diverse diseases, like chronic lymphocytic leukemia and breast cancer." (PMID 37779872, 2023). "Another group demonstrated that TLR9 signaling by CpG-B ODNs leads to NF-kB-dependent production of autocrine IL-10, which then activates JAK/STAT pathway-dependent tyrosine phosphorylation of STAT1 proteins and thereby engenders an apoptotic pathway in human chronic lymphocytic leukemia B-cells." (PMID 23561041, 2013). "Chronic lymphocytic leukemia (CLL) cells possess regulatory functions comparable to those of normal B10 cells, a regulatory B cell subset that suppresses effector T-cell function through STAT3-mediated IL-10 production." (PMID 29379494, 2017).
CNS lymphoma (21 papers, 2014 to 2026). "Another study showed that patients with primary central nervous system lymphomas (PCNSLs) and primary vitreoretinal lymphomas (PVRLs) had similar IL-10 (-1082) A allele frequencies, but their genotype distributions differed from those of the healthy controls." (PMID 36009467, 2022). "Cerebrospinal fluid (CSF) β2‐microglobulin (β2‐MG), soluble IL‐2 receptor (sIL‐2R), and interleukin‐10 (IL‐10) are known to be useful diagnostic biomarkers for CNS lymphoma." (PMID 32314548, 2020). "Rubenstein and co-authors linked the IL-10 gene to primary and secondary CNS lymphomas." (PMID 36009467, 2022). "While the diagnostic value of cerebrospinal fluid (CSF) IL-10 and IL-10/IL-6 ratios has been established in primary CNS lymphoma (PCNSL), their utility in predicting CNS relapse in SCNSL remains underexplored." (PMID 40881684, 2025). "CSF-CXCL13 is discussed to be a helpful diagnostic biomarker together with CXCL9, β2-microglobulin, soluble interleukin-2-receptor, and interleukin-10 in CNS lymphoma." (PMID 38203597, 2023). "Concentrations of IL-10 in the cerebrospinal fluid in primary or secondary CNS lymphoma were also significantly higher than in samples from healthy subjects." (PMID 36009467, 2022). "The CSF IL-10 concentration was dramatically decreased by the zanubrutinib monotherapy, which was related to the control of CNS lymphoma and demonstrates the significant anti-tumor activity of zanubrutinib." (PMID 35004280, 2021). "CXCL13 in combination with IL10 is upregulated in primary CNS lymphoma, and in this combination is specific for the disease." (PMID 31916298, 2020). "A relatively large study (n = 220) showed a high specificity of CSF CXCL13 level, and the combination of CXCL13 and IL‐10 is highly useful for the diagnosis of CNS lymphoma." (PMID 32314548, 2020). "Notably, increased CSF IL-10 has been proposed as a potential biomarker for CNS lymphoma, including SCNSL." (PMID 40881684, 2025). "According to several studies, STAT6 activation (p-STAT6) in M2 macrophages of patients with acute liver failure and in the cerebrospinal fluid of those with primary central nervous system lymphoma significantly correlates with the presence of interleukin -10 (IL-10)." (PMID 37461040, 2023). "IL-10 is the established diagnostic biomarker for VRL (90% detection in cases with vitreous opacity and subretinal infiltration), despite the limitation that elevated vitreous IL-10 level is not diagnostic of intraocular or central nervous system lymphoma." (PMID 32545709, 2020). "Additionally, accumulation of studies is warranted to give definitive conclusion on the impact of CSF IL-10 in prognosis of CNS lymphoma." (PMID 27924864, 2016). "IL-10/IL-6 ratio, which is one of the indicators of poor prognosis of DLBCL, increased in the CSF of primary CNS lymphoma (PCNSL) patients." (PMID 35280688, 2022). "Elevated cytokines in CSF, such as macrophage-colony stimulating factor, interferons, interleukin-10, and soluble interleukin-2 receptor, could differentiate NMOSD from MS, and CNS lymphoma." (PMID 33281722, 2020). "The only case of PTL with an elevated CSF IL-10 level was not included due to suspected secondary CNS lymphoma." (PMID 27924864, 2016).
diabetic nephropathy (21 papers, 2013 to 2025). "Interleukin-10 (IL-10) level per se is found significantly elevated in diabetic nephropathy patients with association to IL-10 −592 C/C genotype." (PMID 30873205, 2019). "Association of interleukins including IL-4 and IL-10 with diabetic nephropathy was also investigated in two studies." (PMID 26587547, 2015). "In this meta-analysis, variants within or near VEGFA (two variants), CCR5 (two variants), CCL2, IL-1, MMP9, EPO, IL-8, ADIPOQ and IL-10 were significantly associated with diabetic nephropathy." (PMID 25280384, 2014). "Although another less characterized IL-10 gene SNP rs3021094 (3388 A/C) at the intron region has been reported to show a weak association with diabetic nephropathy in Chinese population, the significance of this SNP has not been established with other diseases previously." (PMID 30873205, 2019). "In kidneys, IL-10 is secreted primarily by mesangial and endothelial cells, and several studies have reported that elevated IL-10 expression is associated with various kidney diseases, such as mesangioproliferative glomerulonephritis, IgA nephropathy, and diabetic nephropathy." (PMID 36142626, 2022). "Ethanol extracts of L. japonica were also found to elevate IL-10 in STZ-induced diabetic nephropathy rats, effectively mitigating DKD-related inflammation." (PMID 41459479, 2025). "In agreement with our studies, reports have shown that IL-10 production is elevated in T1D patients compared to controls as well as in T1D diabetic nephropathy." (PMID 36766809, 2023). "Elevated levels of serum IL-10 have also been found in other kidney diseases, such as mesangioproliferative glomerulonephritis, IgA nephropathy, and diabetic nephropathy." (PMID 34868046, 2021). "The following genes had significant association with diabetic nephropathy: eNOS, AT2R, SUMO4, IL-10, VEGF, MTHFR, ACE, and VDR." (PMID 26587547, 2015). "In addition, tetrandrine can reduce the levels of inflammatory factors TNF-α and IL-6 and elevate IL-10 level in rats with diabetic nephropathy (DN)." (PMID 35722158, 2022). "Moreover, 20 mg/kg maslinic acid treatment upregulated both the protein and mRNA levels of IL-10 in the renal tissues of diabetic nephropathy mice." (PMID 35042497, 2022). "Serum bilirubin levels are positively correlated with the levels of the antioxidative enzymes as superoxide dismutase, catalase, and glutathione peroxidase, while it is inversely correlated with C-reactive protein, TNF-α, interleukin (IL)-2, IL-6, and IL-10 release in diabetic kidney disease." (PMID 35327498, 2022). "Therefore, IL-10, as an immunoregulatory cytokine, may be correlated with diabetic nephropathy and its anti-inflammatory properties have been similarly demonstrated in animal models." (PMID 23762850, 2013). "The inhibitory effects on the levels of interleukin-2, interleukin-6, interleukin-10, and tumor necrosis factor-α in serum and kidney revealed the protection of PHC against diabetic nephropathy." (PMID 27034961, 2016).
encephalomyelitis (21 papers, 2009 to 2025). Inflammation of the brain and the spinal cord. "In addition, IL‐10 has a protective immune modulatory role against neuro‐adapted Sindbis virus‐associated encephalomyelitis." (PMID 31015278, 2019). "IL-10 suppresses the development of Th1 and Th17 cells that can be mediators of immune pathology, and mice deficient in IL-10 develop accelerated fatal encephalomyelitis after NSV infection associated with an early increase in pathogenic Th17 cells, neutrophils and Il17a mRNA." (PMID 36016413, 2022). "In encephalomyelitis induced by the TE12 strain of SINV that has intermediate virulence, IL-10 deficiency led to more severe disease associated with an increase in Th1 responses." (PMID 36016413, 2022). "IL-10 is increased in the CNS during SINV encephalomyelitis and is an important modulator of CD4+ T cell responses and disease severity during CNS infection with strains of SINV that differ in virulence." (PMID 36016413, 2022). "Referring to this, in Theiler’s murine encephalomyelitis (TME) an enhanced expression of IL-10 has been measured in the brain of SJL mice." (PMID 27611574, 2016). "Whereas the encephalomyelitis was worse in IL-10-/- mice, the oral administration of myelin glycoprotein of oligodendrocytes (MOG 35–55) result in improvement of disease in all groups." (PMID 26115356, 2015). "Meanwhile, the increased production of IL-4, IL-10 and TGF-β has been shown to modulate encephalomyelitis (EAE)." (PMID 33639942, 2021). "On the other hand, even though there was some IL-10 production by cultures from the BCG group, the levels of this cytokine were significantly high in all groups with encephalomyelitis, independently of a previous immunization." (PMID 24288555, 2013). "Previously immunized groups, that were later submitted to encephalomyelitis induction presented lower IFN-γ and IL-10 levels in comparison to the control EAE group." (PMID 24288555, 2013). "Previous studies have shown that the production of IL-10, a cytokine that controls inflammation in part by regulating differentiation of CD4+ T cells, is an important determinant of the outcome of SINV-induced encephalomyelitis." (PMID 36016413, 2022).